GSK3B (glycogen synthase kinase 3 beta)
Diseases named in the same sentence as GSK3B in open-access papers (continued):
Sharing a sentence is not in itself a finding about the gene and the disease.
cancer (continued). "Our previous studies found that increased expression of total GSK3β and its active fraction (pGSK3βY216) is a distinct feature of many cancer types [reviewed in 7, 9, 11] including CRC." (PMID 29568361, 2018). "In our search for active natural products against neurological and cancer disorders, we have discovered the potency of Amaryllidaceae alkaloids to inhibit GSK-3β." (PMID 29561817, 2018). "Activation of GSK3β leads to phosphorylation of β-catenin, an important transcription factor regulating the G1/S transition by cancer cells." (PMID 29324748, 2018). "In some other cancer cell types, CaMKKβ and glycogen synthase kinase-3β (GSK-3β) were identified as upstream regulators of AMPK activation, proteasome inhibition was linked to a decrease in GSK-3β activity and to the activation of AMPK and autophagy." (PMID 30333975, 2018). "It has been reported that the Gemcitabine resistance in PaCa has a close relationship with Akt-GSK3β-Snail pathway activity, and it has been shown that oxaliplatin induces an epithelial–mesenchymal transition in cancers." (PMID 29949874, 2018). "The cell cycle arrest induced in cancer cells by GSK3β inhibition suggests a mechanistic role of this kinase in the biodynamic process of mitosis." (PMID 29568361, 2018). "GSK3β is a ubiquitously expressed serine/threonine protein kinase that is important for establishing chemo- or radio-resistance in cancers." (PMID 30195772, 2018). "A recent study reported the therapeutic effect of GSK3β inhibition on cancer via disruption of centrosome homeostasis resulting in mitotic catastrophe." (PMID 29568361, 2018). "With regard to the mechanism by which miR-137 regulates the MMP-2 and, subsequently, causes the suppression of cancer invasion by ISO treatment, we discover that GSK3β plays an essential role in mediating these observed effects." (PMID 30195772, 2018). "The regulatory role of GSK‐3β on NF‐κB and inflammatory response have recently been established in the immune response, cell survival and cancer." (PMID 28714566, 2017). "It is phosphorylated and destabilized by CK1 and GSK3B, with stabilized CTNNB1 reported as a hallmark of many cancers." (PMID 28174229, 2017). "Our present study reinforces the cancer therapeutic effect of GSK3β inhibition by repurposing these medicines for GBM." (PMID 28423558, 2017). "Peptides corresponding to the DEAD box helicase domain of CAGE, such as AQTGTGKT, QTGTGKT and TGTGKT, also showed anti-cancer activity by preventing CAGE from binding to GSK3β." (PMID 28099142, 2017). "We were interested to examine the mechanism of anti-cancer drug-resistance conferred by CAGE.We present evidence that CAGE confers anti-cancer drug-resistance by binding to GSK3β and increasing the expression of cyclin D1 and pGSK3βSer9." (PMID 28099142, 2017). "Each of the GSK3β-inhibiting medicines has unique cancer therapeutic mechanisms other than its GSK3β-inhibitory effect." (PMID 28423558, 2017). "The phosphorylation of GSK3β has been explored in many cancers as an initiator for promoting EMT phenotypes." (PMID 29250491, 2017). "This has profound implications for GSK3β as a drug target in cancer and other pathologies, and for understanding miR biogenesis as a highly complex and stringently-controlled process on which a multitude of vital signalling cascades converge." (PMID 27907888, 2017). "SCD1 also controls cancer cell proliferation through the modulation of other downstream targets of Akt, such as GSK3β." (PMID 29354058, 2017). "GSK3β is one of the major downstream targets of Akt and is involved in migration and proliferation of cancer." (PMID 28134352, 2017). "Although this clinical study has limitations such as single institution and small number of patients enrolled, it was first to provide the evidence of GSK3β-targeted cancer therapy based on drug repositioning." (PMID 28423558, 2017). "PI3K/AKT/GSK3β/β-catenin signaling is activated in most cancers, especially in gastrointestinal tumors." (PMID 29358963, 2017).
cancer (continued). "Our results showed that PIWIL2 can significantly up-regulate phosphorylation level at Ser9 of GSK3β in germ cells and cancer cells." (PMID 28903391, 2017). "Recent studies pointed out that Erk1/2 and GSK3b pathways are regulated by sCPE, mainly affecting cancer cell survival." (PMID 28978054, 2017). "We therefore examined the potential of GTGKT peptide as anti-cancer peptide in association with its potential effect on the expression of cyclinD1 and the binding of CAGE to GSK3β." (PMID 28099142, 2017). "Inhibition of SCD1 in cancer cells leads to dephosphorylation and activation of GSK3β, which halts cell proliferation by inducing β-catenin and cyclin D1 ubiquitinylation and degradation." (PMID 29354058, 2017). "Abnormal GSK-3β expression has been observed in a variety of cancers, including pancreatic, colorectal and ovarian." (PMID 28930226, 2017). "The regulatory network analysis showed the association of some important hub proteins like GSK3B, NUMB, PEG3, ITGA2 and DLG2 with cancer-associated pathways." (PMID 28587194, 2017). "Increasing evidence points towards a pro-oncogenic role of GSK3β in various cancer types due to its effects in promoting cell proliferation and survival." (PMID 27602497, 2016). "Our results show that treatment with a combination of TRAIL and TZD which induces potent apoptosis, also antagonized the expression of total GSK3β in various cancer cells." (PMID 27602497, 2016). "The development and indication of GSK-3β inhibitors for the treatment of chronic diseases such as cancer requires a strong awareness of safety issues." (PMID 27780915, 2016). "The mechanistic insight in this study provides evidence, for the first time, that PON2 expression in human tumors and cancer cell lines is, at least in part, mediated by the Wnt / GSK-3β / β-catenin pathway." (PMID 27322774, 2016). "Hyperactivation of the Wnt / β-catenin signaling pathway leads to blockade of the kinase GSK-3β and results in a disproportionate activation of proliferative and anti-apoptotic factors, which contribute to the development of various types of cancer." (PMID 27322774, 2016). "We also examined eIF2α, GSK3β, and I-2 in the second cancer line (SKOV3), and obtained the same results: they were all under-phosphorylated in the OLA1-KD cells as compared with the control cells." (PMID 26655089, 2016). "GSK-3β, which mediates Akt signaling and prevents β-catenin phosphorylation and degradation, is aberrantly activated in many types of cancer." (PMID 27750216, 2016). "Collectively, these results suggest that lithium reduces the expression of TGFBIp in cancer cells by inhibiting the TGFβ1-Smad3 signaling pathway through the inactivation of GSK3β." (PMID 26857144, 2016). "GSK-3β has been investigated as a therapeutic target for numerous human diseases, including cancer, because of its diverse cellular functions." (PMID 27050373, 2016). "The defective activation of AKT finally results in reduced GSK3β phosphorylation, prevention of G1/S transition and inhibition of cancer cell growth." (PMID 27809307, 2016). "Based on the pioneering study showing that GSK- 3β is required for NF-κB activation in mouse embryonic hepatocyte survival, previous studies focused on the role of GSK-3β in regulating NF-κB activity in cancer cells." (PMID 27780915, 2016). "GSK3β and SFRP2 are important effectors of numerous miRNAs in human cancers, so we need to further explore the biological effects of miR-224 on GSK3β and SFRP2 in a reverse logic." (PMID 26822534, 2016). "Glycogen synthase kinase-3 beta (GSK-3β) is a serine/threonine kinase, plays an important role in the initiation, progression and malignancy of many cancers." (PMID 27259701, 2016). "More importantly, the study revealed the fundamental finding of an overall Wnt/GSK3β/β-catenin dependent regulation of PON2 in different cancers, which was confirmed by systematic and multimethodological approaches." (PMID 27322774, 2016).
cancer (continued). "Altogether these results suggest that CCAR2 depletion reduces AKT activation and consequently GSK3β phosphorylation, finally preventing G1/S transition in cancer cells." (PMID 27809307, 2016). "Taken together, we propose that septins, nucleolin and GSK3β are the most important targets for 3MCIC to exert its cytotoxic effect toward cancer cells." (PMID 27525972, 2016). "Together with other studies, our observations have established GSK-3β as a potential therapeutic target in common adult-onset chronic diseases including cancer." (PMID 27780915, 2016). "In an attempt to overcome this limitation of GSK3β inhibitors, in the current study we aimed at elucidating the mechanism by which GSK3β expression can be antagonized in cancer cells." (PMID 27602497, 2016). "Immunohistochemically, nuclear localization of β-catenin in the cancer cells was frequently observed in tumors treated with GSK-3β inhibitors, whereas weak cytoplasmic expression was found in control tumors." (PMID 27780915, 2016). "GSK3β has long been considered as an important anticancer target, since its inhibitors have shown promising therapeutic potentials for certain cancer types." (PMID 27525972, 2016). "There is increasing evidence which indicates that GSK3β activity modulates the effectiveness of chemotherapy on cancer cells." (PMID 27195613, 2016). "It has been shown to induce cell growth arrest, apoptosis, generation of ROS, and terminal differentiation in various human malignant tumors by targeting GSK-3β." (PMID 27579985, 2016). "It is unclear who the mediators are downstream of TZD or TRAIL-TZD that regulate GSK3β expression in the cancer cells." (PMID 27602497, 2016). "These suggested that TRAIL-TZD-induced modulation of GSK3β pathway is present in various cancer cells and is a generalized event." (PMID 27602497, 2016). "The AKT/GSK3β pathway promotes cancer progression, including cellular proliferation, growth, survival, and drug resistance." (PMID 26758421, 2016). "Although the exact role of GSK-3β/β-catenin in cancer metastasis remains controversial and is likely cell type- and stimulus-dependent, our study revealed that Akt/GSK-3β/β-catenin is crucial for visfatin induced EMT of CRC cells." (PMID 27058759, 2016). "In summary, for the first time, we demonstrated that AQP3 increases CD44 expression through Wnt/GSK-3β/β-catenin signaling pathway and promotes the stem-like properties of cancer cells in GC." (PMID 26918728, 2016). "A similar nuclear distribution was found for human phospho-Thr390 GSK3β in a human cancer cell line following treatment with doxorubicin, and this was prevented by inhibiting ATM." (PMID 26822034, 2016). "Dysregulated phosphorylation of GSK-3β observed in HBP carcinomas in the present study can prevent Thr286 phosphorylation leading to nuclear accumulation of cyclin D1 and cell cycle progression." (PMID 26902162, 2016). "Here, we report for the first time, inactivation of GSK-3β during the stepwise evolution of HBP carcinomas based on increased levels of p-GSK-3βSer9 with concomitant decrease in p-GSK-3βTyr216." (PMID 26902162, 2016). "In this study, we investigated the molecular and biological responses to a GSK-3β inhibitor by various cancer cell lines to identify the primary molecular pathway responsible for its antiproliferative effects." (PMID 26292722, 2015). "By acting as a core component of the regulatory loop, ILK promotes the aggressive and metastatic phenotype of cancer cells in a hypoxic setting through multiple oncogenic signaling pathways, including those mediated by Akt, GSK3β, and YB-1." (PMID 25821081, 2015). "This advocates that irrespective of its expression levels, GSK3α, in addition to GSK3β should be taken into confidence while targeting GSK3 for cancer therapy." (PMID 25714023, 2015). "Glycogen synthase kinase-3 beta (GSK-3β) has been investigated as a therapeutic target for numerous human diseases including cancer because of their diverse cellular functions." (PMID 26292722, 2015).
cancer (continued). "miR-122 suppresses IGF-1R expression and attenuates IGF-1R/Akt signaling, which sustains the activity of glycogen synthase kinase 3 beta and in turn represses cancer cell proliferation." (PMID 26302777, 2015). "In the OTSCC progression model, a total of twenty-two samples were analyzed, and GSK3β overexpression was observed in 14.2% (1/7) of normal samples, in 20.0% (1/5) of hyperplasia and 70.0% (7/10) of cancer samples (p = 0.0396)." (PMID 25645517, 2015). "Because AR-A0114418 induces DNA aneuploidy and chromosomal instability in cancer cells, there was concern regarding possible carcinogenic activity by GSK-3β inhibition in healthy tissues." (PMID 26292722, 2015). "The Akt/GSK3β pathway is one important signal transduction pathway for chemoprevention and cancer treatment studies." (PMID 26452029, 2015). "In this study, we investigated the anticancer effects of GSK-3β inhibitors on cancer cell lines and observed centrosome dysregulation which resulted in abnormal mitosis." (PMID 26292722, 2015). "Although GSK-3β affects the signalling pathways that regulate the proliferation and survival of cancer cells, the precise role of GSK-3β in cancer pathophysiology remains controversial." (PMID 26292722, 2015). "In general, cancer-associated pathways are altered by inducing intracellular signalling mediators such as ERK, PI3K, Akt and GSK3β." (PMID 25738875, 2015). "Glycogen synthase kinase-3β (GSK-3β), a serine/threonine protein kinase, has been regarded as a potential therapeutic target for multiple human cancers." (PMID 25002914, 2014). "Both GSK3β and β-catenin are key molecules of the canonical Wnt pathway implied in many human cancers." (PMID 25277196, 2014). "As the involvement of GSK-3β in the regulation of NF-κB activity is known to be significant for cancer cell growth, we investigated the levels of NF-κB pathway including Bcl-2 and survivin in LiCl treated SW480 cells." (PMID 25002914, 2014). "This information holds promise for therapeutic modulation of GSK3β/β-catenin-pathway-dependent invasiveness in cancer cells." (PMID 24666969, 2014). "A, previous report showed that the expression of p16INK4a was down regulated under hypoxia/anoxia (0,1%O2), which was dependent on constitutive activation of PI3K/Akt and phosphorylation of GSK3β in cancer cells." (PMID 24984035, 2014). "Anti-cancer activity of MRBE is associated with ROS-dependent cyclin D1 proteasomal degradation and ROS/ GSK3β-dependent ATF3 expression." (PMID 24962785, 2014). "As a key component of this pathway, GSK3β has emerged as a potential therapeutic target for cancer treatment." (PMID 24335145, 2014). "We also noticed that there was cross-talk between the PI3K/Akt and Wnt pathways via GSK-3β, which can possibly expand and enhance the inhibitory effects of miR-34 in cancers 11,12." (PMID 25213795, 2014). "LiCl has been shown to induce cell growth arrest, apoptosis, and terminal differentiation in various human malignant tumors by targeting GSK-3β." (PMID 25002914, 2014). "Studies have identified that inhibitors of the PTEN/Akt/GSK3β signaling cascade and regulation of β-catenin act as potential agents to effectively target cancer stem cells and tumorigenic cancer cells." (PMID 25149539, 2014). "GSK-3β, a multifunctional kinase of cancer, is constitutively activated because of tyrosine-216 phosphorylation, resulting in the phosphorylation of β-catenin." (PMID 25238260, 2014). "rVP1 inhibits cancer cell migration/invasion by downregulating integrin/FAK/Akt/GSK-3β signaling and MMP-2 activity." (PMID 25004182, 2014). "Differential expression and regulation of GS3β in cancer appear to be tissue specific and involved in inducing molecular genetic heterogeneity, as certain forms of cancer showed high expression of active GSK3β; however, other cancer tissues harbor low levels." (PMID 24550987, 2014).
cancer (continued). "In this study, we analyzed downstream signals of AMPK to search for naturally originating novel modulators of the AMPK/GSK3β/β-catenin pathway to control cancer cell proliferation and metastasis." (PMID 24666969, 2014). "So we used LiCl to inhibit the activity of GSK-3β pharmacologically and found the increased generation of ROS, which implied the involvement of ROS in inactivation of GSK-3β in the regulation of cancer development." (PMID 25002914, 2014). "Taken together, our findings suggest that AMPK-mediated regulation of GSK3β is responsible for the anthocyanin-induced decrease in the proliferation and metastatic potential of hepato-carcinoma cells." (PMID 24666969, 2014). "In a cancer cell, activated Akt will phosphorylate GSK3β, thus inhibiting its function in the degradation of β-catenin and c-myc." (PMID 23690850, 2013). "Despite its role in destabilizing cyclin D1 in physiological cells, inhibition of GSK3β decreases cyclin D1 expression in cancer cells." (PMID 23408967, 2013). "Consistently, the animal studies showed little detrimental effects of GSK3β inhibition on normal cells and vital organs, leading to promotion of future clinical application of cancer treatment targeting GSK3β." (PMID 23408967, 2013). "Inhibition of GSK3β significantly reduced the proliferation and survival of cancer cells, sensitized them to gemcitabine and ionizing radiation, and attenuated their migration and invasion." (PMID 23408967, 2013). "The levels of glycogen synthase (GS) phosphorylated at Y641 (p-GSS641) and p-β-cateninS33/37/T41 decreased in cancer cells following treatment with AR-A014418, indicating its activity against GSK3β in cancer cells." (PMID 23408967, 2013). "Inhibition of GSK3β attenuated cancer cell migration and invasion in wound-healing and transwell assays." (PMID 23408967, 2013). "The effects of GSK3β inhibition on cancer cell survival, proliferation, invasive ability and susceptibility to gemcitabine and radiation were examined following treatment with a pharmacological inhibitor or by RNA interference." (PMID 23408967, 2013). "Even though it has been widely accepted that the aberrant GSK3β-mediated functions are often related to carcinogenesis, the utilization of GSK3β antagonists in cancer therapies remains enigmatic and controversial." (PMID 24312384, 2013). "Together, these results demonstrate that combined treatment with GSK3β inhibitor sensitizes cancer cells to gemcitabine and to ionizing radiation." (PMID 23408967, 2013). "Further work is required to clarify the putative roles for GSK3β in regulating cytoskeletal structure, cell polarity and motility and its promotion of cancer cell migration and invasion." (PMID 23408967, 2013). "The present study confirmed previously reported roles for GSK3β in cancer cell survival and proliferation." (PMID 23408967, 2013). "In certain cancers, GSK3β functions as a tumor suppressor gene and its inactivation is associated with Cdc25a overexpression." (PMID 23941783, 2013). "We therefore investigated the effect of GSK3β inhibition on FAK activity in cancer cells responding to wound stimulation by determining the levels of p-FAKY397 and p-FAKY861." (PMID 23408967, 2013). "Although its role in cancer is still debated, the overall results so far indicate that aberrant expression and activity of GSK3β is a common and fundamental characteristic in a broad spectrum of cancers." (PMID 23408967, 2013). "Depletion of GSK3β by RNA interference attenuated cell viability and proliferation in all cancer cell lines." (PMID 23408967, 2013). "In contrast, accumulating evidence suggest that GSK3β functions as an oncogene and promotes proliferation and augments cell survival, and has been proposed as a potential therapeutic target for cancer treatment." (PMID 23941783, 2013). "We investigated expression of the EMT-related molecules E-cadherin, N-cadherin and vimentin in cancer cells following treatment with AR-A04418 and GSK3β-specific siRNA." (PMID 23408967, 2013).